VIM (vimentin)
Diseases named in the same sentence as VIM in open-access papers (continued):
Sharing a sentence is not in itself a finding about the gene and the disease.
tumor (continued). "Importantly, their target antigens seem to be expressed by the epithelial tumor cells, highlighted by either EpCAM or CA125 epithelial cell markers, and not by the vimentin-expressing tumor stroma." (PMID 39086481, 2024). "However, targeting VIM is not just limited to the cell surface, as targeting the intracellular, cytoplasmic VIM using withaferin-A or FiVe1 also results in robust anti-tumor responses." (PMID 39766058, 2024). "Furthermore, circKEAP1 did not exert tumor suppressor effects when cells were transfected with vimentin in vivo and in vitro." (PMID 38383479, 2024). "Tumor cells in both cases were positive for vimentin and negative for PanCK." (PMID 38854270, 2024). "Because EMT initiation is a critical process in tumour progression, we evaluated the effect of BEST4 on EMT using quantitative polymerase chain reaction (qPCR) and found that BEST4 expression upregulated CDH1 and TJP1 and downregulated VIM and TWIST1 in HCT116 compared with the control (p<0.05)." (PMID 39699952, 2024). "Importantly, the absence of VIM expression significantly diminished tumor growth in CAM, as well as of neoformed blood vessels." (PMID 36594099, 2023). "However, the tumor was postoperatively diagnosed as SSCT, which pathologically consisted of a tubular pattern with regular nuclei and embedded in a densely collagenous stroma, as well as diffusely positive for vimentin, β-catenin and synaptophysin." (PMID 37189109, 2023). "In the current study, using TMAs and specimen slides from a relatively large cohort (N = 192) of primary resected SCLC, we assessed the tumor‐derived protein expressions of ASCL1, NEUROD1, POU2F3, YAP1 as well as VIM, a mesenchymal marker which may be a potential assay to define SCLC‐I." (PMID 37789961, 2023). "Furthermore, a recent study revealed that immunizing with a combination of citrullinated enolase and vimentin peptides could stimulate strong CD4+ T-cell responses and potent anti-tumour effects, which may prevent tumour antigen escape." (PMID 37778382, 2023). "Staining for EpCAM and CD24 alongside the mesenchymal marker Vimentin in over 12,000 imaging fields from 74 human tumours, stratified on metastatic status, identifies cells that have undergone EMT and disseminated into the stromal region surrounding metastatic primary tumours." (PMID 37975646, 2023). "The outcomes of IHC revealed that the Ki67 and Vimentin abundances were lesser, but c-caspase 3 contents were higher in the sh-circNFATC3 group, which indicated that the absence of circNFATC3 subdued tumor growth and invasiveness but promoted apoptosis in vivo." (PMID 37398901, 2023). "Thus, tumor cells subjected to EMT show a series of molecular changes characterized by decreased expression of epithelial markers, as E-cadherin, ZO-1 and occludin, and increased expression of mesenchymal markers as N-cadherin, vimentin and fibronectin." (PMID 36769105, 2023). "Tumor‐derived Vimentin (VIM) was nearly expressed in triple‐negative SCLC tumors." (PMID 37789961, 2023). "Thus, inhibiting the expression of TYRO3 in H-DR and T-DR could promote the expression of E- Cadherin and reduce the expression of Vimentin, suggesting the inhibition of the EMT process of tumor cells." (PMID 37116196, 2023). "Furthermore, the WB analysis showed that the expression levels of vimentin, PIAS1, P62, cathepsin B and D, SUMO2/3, SUMO1, and CDC42 were lower in the xenograft tumor tissues of Hct116 and LoVo control cells than in the PDCs." (PMID 37833712, 2023). "Indeed, vimentin regulates the expression of the EMT-related transcription factors including Slug, which results in markedly elongated morphology of tumor cells and induces the expression of Axl, a receptor tyrosine kinase that is stimulated by the secreted protein growth arrest-specific 6 (Gas6)." (PMID 38313431, 2023).
tumor (continued). "Hematoxylin and eosin (H&E) stain, both the PDSOs and matched patients’ tumor showed atypical spindle cell proliferation in LMS, LS, and DFSP patients.Both PDSOs and patients’ tumor displayed similar expression of markers, including Ki67, CD34, PARP1, VIM, and MMP9." (PMID 37686615, 2023). "Since EMT is a putative molecular mechanism that drives tumor migration and invasion, we explored whether the EZH2/miR-138-5p axis is involved in EMT by analyzing levels of EMT markers including E-cadherin, N-cadherin, vimentin, and Snail." (PMID 36071871, 2022). "Since there was evidence of scar tissue formation but no intact tumor cells on histology at day 7 post-histotripsy, the expression of vimentin at the periphery of the ablation zone on day 2, and in the ablation zone on day 7, suggests that tissue healing is the likely process." (PMID 35406383, 2022). "Western blot analysis further showed that MG treatment downregulated the expression of vimentin, MMP-2 and MMP-9, and upregulated the expression of E-cadherin and TIMP-2, indicating that MG significantly inhibited the EMT and ECM degradation, and prevented tumor metastasis." (PMID 35770085, 2022). "Finally, we performed immunohistochemistry on L5, L6 and L7 tumor sections to analyze the expression of ZEB2 (for which we could not find an efficient antibody batch for immunoblotting), E-Cadherin and Vimentin respectively in tumor and stromal cells." (PMID 35837106, 2022). "Tumor biomarkers (CK18/PD-L1/EpCAM/AFP) and endothelial cell biomarker CD31 are heterogeneously localized in the cytoplasm, on the nuclear envelope, or in the nuclei, while stem cell biomarker CD133 and mesenchymal cell biomarker Vimentin mainly showed an intracellular distribution." (PMID 35311070, 2022). "Active secretion of vimentin from (tumor) ECs, was not reported to date." (PMID 35606362, 2022). "IHC staining of tumor sections of xenografts and metastasized organs demonstrated that the upregulation of EBV-miR-BART-22 overtly reduced E-cadherin expression but increased the expression of N-cadherin and vimentin in CNE-1-BART22 tumors compared with the CNE1-mock control tumors." (PMID 35907914, 2022). "In this case, the tumor cells strongly expressed vimentin but they were negative for CD34." (PMID 36134098, 2022). "Group 1 comprises epithelial tumor cells that did not express vimentin." (PMID 35440541, 2022). "In CRC, it has been found that miR-17-5p overexpression in tumor cell lines significantly decreased vimentin mRNA and protein expression, cell migration, and invasion, whereas downregulation of miR-17-5p in CRC cell lines increased vimentin protein expression, cell migration and invasion in vitro." (PMID 36555840, 2022). "In addition to the increased expression of the prospective prostate CS/IC marker CD133, tumor hybrids also exhibited a decreased E-cadherin expression, but increased protein levels of AKT, MMP9, and vimentin, suggesting that hybrids may have undergone EMT." (PMID 35562905, 2022). "Indeed, tumor cell spheroids are formed with epithelial adhesion by E-cadherin and EpCAM while simultaneously expressing mesenchymal marker vimentin, indicating that a hybrid/partial EMT status may be essential for tumor and spheroid formation." (PMID 36552758, 2022). "This avoids background staining since it shows no cross reaction with mouse vimentin in tumor stroma or blood vessels, and also because vimentin is expressed on all transformed EC epithelial cells since the endometrium derives from the mesoderm layer in the embryo." (PMID 35884987, 2022). "Our study investigated the links between RBM24 expression and TGFβ-induced EMT, given the significance of EMT in tumor metastasis and former research showing that RBM24 overexpression could upregulate E-cadherin expression but downregulate Vimentin expression in HCT116 human CRC cells." (PMID 36213838, 2022).
tumor (continued). "During the tumor progression and metastasis stages, EMT is a key process by which epithelial cells become detached since they lose their polarity due to the reduction of their expression of E-cadherin and increase in mesenchymal characteristics due to increased expression of N-cadherin and vimentin." (PMID 35672776, 2022). "Negative vimentin expression correlates with tumor metastasis and worse overall survival in EC, suggesting that it may be an excellent prognostic biomarker for this disease." (PMID 35320951, 2022). "Instead, cold TME C1 contained the highest percentage of Community 6 that was characterized by CAIX+ tumor cells in close contact with MC2 and Collagen+ stromal cells; and C2 was mostly dominated by Community 4 enriched for networks of Vimentin+ stromal cells and HLA-DR−VEGF+ myeloid cells MC2." (PMID 36281356, 2022). "The study reported the presence of vimentin in detached and circulating tumor cells, suggesting acquisition of a cancer stem cell-like phenotype by these cells that co-expressed vimentin, CD44, and VE-cadherin at the periphery of tumor islands and invasive fronts." (PMID 35207438, 2022). "The absence of vimentin had a stronger effect on tumor number and size 100 days upon the treatment." (PMID 35399505, 2022). "We found that the knock down of FAM83B significantly affect normal and tumor thyroid cell differentiation, inducing in NTHY-ORI a reduction in the expression of the thyroid marker genes PAX8 and NIS, and in TPC1 cells a significant increase in the expression of the mesenchimal marker vimentin." (PMID 35597845, 2022). "Recent findings have shown that vimentin is not only a passive marker of carcinomas and EMT, but might also induce changes in cell shape, adhesion and migration—as well as promoting the invasion of tumour cells." (PMID 35216078, 2022). "When EMT transcription is activated, intercellular adhesion proteins such as E-Cadherin are down-regulated and EMT markers such as N-Cadherin and vimentin are increased, which may induce HCC dedifferentiation and increase tumor invasiveness, which leads to the occurrence of MVI." (PMID 35392229, 2022). "In the current study, all PRNRP cases exhibited a diffuse and strong expression of PAX8, CK7, and GATA3, whereas the expression of AMACR, CD10, and vimentin was either absent or only weak and focal, and the tumor cells were completely negative for CD117 and CAIX." (PMID 35936734, 2022). "Immunohistochemically, tumor cells were positive for cytokeratin and vimentin, but negative for cytokeratin 7 (CK 7), thyroid transcription factor-1 (TTF-1), carbonic anhydrase-9 (CA-9), paired box gene 8 (PAX8), leukocyte common antigen (LCA), and human melanoma black 45 (HMB45)." (PMID 33950950, 2021). "Elemene reduced metastatic tumor nodules in a mouse metastasis model constructed with SGC7901/ADR cells and reduced the expression of miR-1323, Cbl-b, and E-cadherin in the lungs of nude mice, whereas vimentin, MMP-2, and MMP-9 were significantly downregulated." (PMID 34641334, 2021). "Similarly, compared with the xenograft tumours from mice injected with the saline solution, the tumour tissues from the CVB-treated mice presented substantially decreased numbers of IGFBP3-, Snail-, Vimentin- and Ki-67-positive cells." (PMID 34512163, 2021). "MiR-340 is a recently recognized tumor suppressor which targets and decreases expression of DNMT1, EZH2 and H3K27me3, leading to promoter hypomethylation and expression of E-cadherin as well as decreased expression of mesenchymal markers (N cadherin, vimentin and fibronectin) in TNBC cells." (PMID 33572395, 2021).
tumor (continued). "Although tumor stromal fibroblasts in general may express α-SMA, FAP, vimentin, neuron-glial antigen-2 (NG2) chondroitin sulfate proteoglycan, PDGFRβ, prolyl 4-hydroxylase and FSP1; α-SMA and FAP can be used to discriminate myofibroblasts form fibroblasts in the tumor tissue." (PMID 34336660, 2021). "QRT-PCR results showed that in subcutaneous tumor-carrying tissues, after the Hsp70 knockdown, the expression intensity of E-cadherin in A549 and NCI-H446 cells increased, while the expression level of Vimentin decreased, and the differences were statistically significant." (PMID 34868316, 2021). "Immunohistochemically, tumor cells were positive for vimentin, CD34, but were negative for S-100." (PMID 34909162, 2021). "To learn more about the multifunctional role of the Calebin A, in TME-induced tumor malignancy and metastasis in CRC cells, in relation to motility and EMT, we examined the level of EMT-related pathway protein expression, including E-cadherin, vimentin, and Slug." (PMID 34276382, 2021). "The epithelial cells may express vimentin, whereas a variety of non-epithelial tumor cells are immunoreactive for cytokeratins." (PMID 34203756, 2021). "We identified ZNF471 as a novel potential tumor suppressor gene in CC that inhibits cancer cell growth, proliferation, invasion, and metastasis by arresting cell cycle progression and induction of EMT by up-regulation of CDH1 and downregulation of CDH2, VIM, and TW1." (PMID 33566221, 2021). "In accordance with the in vitro observations, Western blotting of primary tumor, isolated from mice orally administered with or without milk-derived EVs, confirmed the upregulation of senescence regulator p16 and cytoskeletal protein Vimentin." (PMID 34168137, 2021). "However, nowadays it is accepted that, although reactivated in many cancer types, EMT is rarely fully executed in tumor cells, and end‐stage markers such as Vimentin are often not expressed." (PMID 34459003, 2021). "However, in subsequent passages vimentin was expressed in all the tumor cells, more intensely and without specific subcellular localization." (PMID 34198671, 2021). "Additionally, in vivo overexpression of miR-34a attenuated metastasis and angiogenesis of BLCA cells promoting E-cadherin expression, however inhibiting N-cadherin, Vimentin, and β-catenin expression, therefore possibly inhibiting EMT and acting as a tumor suppressor." (PMID 33672684, 2021). "Moreover, E-cadherin level is downregulated, and vimentin expression is up after KIF4A knockdown, suggesting that KIF4A could promote tumor invasion and metastasis through EMT in vitro." (PMID 34775374, 2021). "NSE and vimentin were higher in tumour relative to non-tumour tissue, but not significantly." (PMID 33906633, 2021). "Correlation of HDAC 2 expression with markers of epithelial-to-mesenchymal transition (EMT) and histone methyltransferase G9a was moderate and significant for vimentin (positive correlation) and E-cadherin (negative correlation) when measured at the tumor margins." (PMID 34359763, 2021). "Vimentin is a potential target for cancer treatment since it is critically involved in the cellular processes, such as epithelial-to-mesenchymal transition (EMT), cell migration and invasion, that are the common features of all solid tumors, not limited to a particular tumor type." (PMID 34305581, 2021). "While vehicle-treated samples showed relatively low expression of vimentin on both cell types, following MRTX1257 treatment endothelium became one of the highest expressing cell types and this expression was predominantly within the interface and tumour domain." (PMID 34625563, 2021).
tumor (continued). "The tumor consists of naïve but not sufficient atypia epithelial and mesenchymal components, the epithelial component is positive for cytokeratin, and the mesenchymal component is positive for vimentin and CD10." (PMID 33761637, 2021). "In conclusion, these findings suggest that interplay between PD-L1 and vimentin may exist in non-metastatic NSCLC patients and the positivity of both markers in tumor tissue is associated with a trend towards a worse prognosis." (PMID 34917615, 2021). "Vimentin expression was negative in OPSCC cells in all tumor samples." (PMID 32794417, 2020). "In addition, VWCE promotes tumor cell migration and invasion through EMT, as VWCE overexpression leads to decreased levels of N-cadherin, vimentin, and the EMT-induced transcription factor, ZEB1, as well as elevated E-cadherin levels, indicating a significant inhibition of EMT processes." (PMID 33194737, 2020). "In addition, the ratio of E-cadherin to vimentin is much lower than the corresponding human tumors in TCGA with the exception of RENCA, suggesting that syngeneic models typically have a more mesenchymal-like tumor cellular phenotype than human tumors." (PMID 31898484, 2020). "Interestingly, they also reported that the expression of CD44 and Vimentin was higher in presence of microcalcifications compared with tumor tissue without microcalcifications." (PMID 33203195, 2020). "The tumor cells expressed immunoreactivity for vimentin, but not for S100, CD34, actin, or desmin." (PMID 32605652, 2020). "Evidence of neoplasia in BE and EAC was characterized by reduced gastrointestinal epithelium markers keratin 13 and keratin 20, relative to RE, while epithelial-to-mesenchymal transition markers vimentin and desmin were increased in BE and EAC respectively, compared to control." (PMID 32650561, 2020). "Vimentin up-regulation is an EMT-specific marker of increased cancer cell motility and migration; therefore, its positive staining in NLR-JIMT-MSC-CA xenograft suggests significant functional changes in cancer patients’ MSCs where breast adipose tissue has close proximity to the tumor." (PMID 32093026, 2020). "As tumor cells develop EMT, the cell-to-cell bridge is lost, the expression of epithelial markers such as keratin, E-cadherin, and Epcam decreases, and the expression of mesenchymal marker vimentin increases, and its morphology changes, get rid of the primary tumor and obtain aggressive." (PMID 32972417, 2020). "Our CHCs are different from reported hybrid cells in blood 55, 56 in two aspects: our tumor cells expressed positivity to the pan-leukocyte antigen CD45 and either one of the combinations; CTC epithelial marker E-cadherin or simultaneously, both E-cadherin and the CTC mesenchymal marker vimentin." (PMID 33042268, 2020). "However, no discernible difference in vimentin expression was observed between parent and holoclone tumour pairs in either cell line." (PMID 32647229, 2020). "Furthermore, in evaluation with pT category of cancer by increasing tumor invasion from submucosa (pT1) to tumor invasion to other organs or structure like visceral peritoneum, the Vimentin value did not increase significantly (P value>0.05)." (PMID 32665775, 2020). "Similarly, genetic knockdown of ABCC3 and treatment of the primary cell line with MCI-715 reduced the expression levels of α-SMA and vimentin, in agreement with the hypothesis that ABCC3 is involved in both PDAC tumour and stroma development." (PMID 31378204, 2019). "By contrast, in vivo modulation of tumor cell morphology, E-cadherin and vimentin levels, and the lack of in vitro inhibition of tumor cell proliferation by the LOXL2 inhibitor, point to a possible EMT function rather than proliferative stimulation of tumor cell growth." (PMID 31086173, 2019). "The tumor promoting role of CORO1C might be mediated by cyclin D1 and vimentin." (PMID 30974047, 2019).